SMURF1 (SMAD specific E3 ubiquitin protein ligase 1)
Diseases named in the same sentence as SMURF1 in open-access papers (continued):
Sharing a sentence is not in itself a finding about the gene and the disease.
Cirrhosis (2 papers, 2022 to 2024). A chronic disorder of the liver in which liver tissue becomes scarred and is partially replaced by regenerative nodules and fibrotic tissue resulting in loss of liver function. "Silencing of SNHG1 significantly ameliorates cirrhosis in livers of mice, while miR-15a mimic treatment in BMSCs restrains cirrhosis in mice, suggesting that SNHG1 silencing alleviates cirrhosis via the miR-15a/SMURF1 axis." (PMID 39200161, 2024). "HGF-induced BMSCs with manipulated SNHG1/miR-15a/SMURF1 expression, after 7-d culture in vitro, were injected into mice to observe their effects on cirrhosis in mice." (PMID 35194023, 2022). "LncRNA SNHG1 or SMURF1 silencing or miR-15a overexpression promoted differentiation of BMSCs into HLCs and repressed cirrhosis of mice by upregulating ATG5 and Wnt5a via UVRAG." (PMID 35194023, 2022). "Next, our focus was shifted to the role of the lncRNA SNHG1/miR-15a/SMURF1 axis in cirrhosis in mice." (PMID 35194023, 2022). "Consistently, miR-15a mimic treatment in BMSCs noticeably restrained cirrhosis in mice, whilst simultaneous overexpression of SMURF1 nullified the effect of miR-15a restoration alone." (PMID 35194023, 2022). "Conclusively, lncRNA SNHG1 silencing might facilitate HLC differentiation from mouse BMSCs and alleviate cirrhosis via the miR-15a/SMURF1/UVRAG/ATG5/Wnt5a axis." (PMID 35194023, 2022). "Therefore, our work was designed to figure out impacts of lncRNA SNHG1 on cirrhosis by orchestrating HLC differentiation of BMSCs via miR-15a/SMURF1/UVRAG/ATG5/Wnt5a axis." (PMID 35194023, 2022). "Further, we testified the findings in the cirrhosis mouse model and obtained similar results as in vitro experiments: injection of SMURF1 overexpression HGF-induced BMSCs aggravated the degree of cirrhosis in mice, which was abolished by oe-UVRAG, rapamycin, or recombinant Wnt5a." (PMID 35194023, 2022). "Finally, the downstream mechanism of SMURF1 in cirrhosis was explored." (PMID 35194023, 2022). "Moreover, our data revealed that miR-15a targeted SMURF1, which enhanced ubiquitination of UVRAG, to promote BMSCs to differentiate to HLC in vitro and repress liver fibrosis in mice with cirrhosis." (PMID 35194023, 2022). "Briefly, lncRNA SNHG1 silencing was observed to downregulate SMURF1 by upregulating miR-15a, diminishing ubiquitination of UVRAG to activate ATG5/Wnt5a axis, which accelerated HLC differentiation from BMSCs and repressed liver fibrosis to inhibit cirrhosis." (PMID 35194023, 2022).
COVID-19 (2 papers, 2021 to 2023). A disease caused by infection with severe acute respiratory syndrome coronavirus 2. "We found that WWP1, WWP2, SMURF1, and NEDD4 mRNA are overexpressed in COVID-19 vs. SARS-CoV-2 negative patients in nasopharyngeal and oropharyngeal swab cells, as well as in the lung of affected patients and in mouse models of COVID-19." (PMID 33762578, 2021). "NEDD4 (FC = + 2.06, p ≤ 0.005), WWP1 (FC = + 1.85, p ≤ 0.0005), WWP2 (FC = + 4.11; p < 0.005) and SMURF1 (FC = + 1.7, p ≤ 0.05) showed a significant overexpression in nasopharyngeal and oropharyngeal swabs of COVID-19 positive patients compared to negative patients." (PMID 33762578, 2021).
craniosynostosis (2 papers, 2016 to 2017). Craniosynostosis is defined as the premature fusion of one or more cranial sutures leading to secondary distortion of skull shape resulting in skull deformities with a variable presentation. "Interestingly, we identified one de novo D-mis mutation in SMURF1 in a proband with sporadic metopic craniosynostosis." (PMID 27606499, 2016). "In mice, constitutive activity of BMPR1A in cranial neural crest results in SMAD-dependent development of metopic craniosynostosis, and genetic deficiency for the SMAD inhibitor SMURF1 causes midline craniosynostosis." (PMID 27606499, 2016). "A de novo mutation in SMURF1 was recently reported in a single individual with craniosynostosis; no cardiac features were reported in the proband." (PMID 29089047, 2017).
diabetes (2 papers, 2018 to 2023). "Modulating the Talin-1/Smurf1/Stat3 axis in pancreatic islet β-cells could serve as a promising therapeutic approach for patients with diabetes." (PMID 37903776, 2023). "This is reflected by the increased induction of chemokine transcripts by plasma of siblings with low HLA risk and individuals with diabetes, and elevated induction of regulatory transcripts (IL2RA, CBLB, SMURF1, SMURF2, SKI) by plasma of siblings with high HLA risk and unrelated control individuals." (PMID 30167736, 2018).
Hypertension (2 papers, 2020 to 2023). The presence of chronic increased pressure in the systemic arterial system. "Studies showed that biomarkers include PLD2, FLNA (filamin A), SMURF1, LINGO1, CACNA1H, NLRP6, NLRC3, CXCR2 and C5AR1 plays an important role in progression of hypertension." (PMID 36837510, 2023).
inflammatory bowel disease (2 papers, 2017 to 2024). A spectrum of small and large bowel inflammatory diseases of unknown etiology. "SMURF1 is a protein-coding gene that is associated with inflammatory bowel disease and acts as a negative regulator of the BMP (Bone morphogenetic protein) signaling pathway (regulation of cell motility, cell signaling, and cell polarity)." (PMID 38956704, 2024). "In humans, polymorphisms in several autophagy-related genes, including IRGM, LRRK2, SMURF1 and ATG16L1, leading to autophagy deficiency are linked to inflammatory bowel disease (IBD) susceptibility." (PMID 28916785, 2017).
liver fibrosis (2 papers, 2022 to 2025). "Although other E3 ligases may also interact with TLN1, SMURF1 is of particular interest due to its established roles in TGF-β and Hippo signaling—pathways critically involved in MASLD, liver fibrosis, and HCC." (PMID 41284206, 2025).
osteosarcoma (2 papers, 2017 to 2025). A usually aggressive malignant bone-forming mesenchymal neoplasm, predominantly affecting adolescents and young adults. "Additionally, UBE2V1 promotes osteosarcoma differentiation through Smurf1-dependent ubiquitination and subsequent degradation of Smad1." (PMID 41446875, 2025).
Parkinson disease (2 papers, 2020 to 2022). A progressive degenerative disorder of the central nervous system characterized by loss of dopamine producing neurons in the substantia nigra and the presence of Lewy bodies in the substantia nigra and locus coeruleus. "Overall, the prospect of bone regeneration by small molecules seems to be focused on the role that Smad activators and Smurf1 inhibitors play in the process, which is partly similar to the course of studies in Parkinson's disease therapeutics." (PMID 36545269, 2022). "Given that the clearance of damaged mitochondria is a characteristic of several neurological pathologies, including Parkinson’s disease, further studies are required to investigate the role of the Smurf1 C2 domain in the fusion of lipid membranes and the ability to target lysosomal membranes." (PMID 32033048, 2020).
pulmonary fibrosis (2 papers, 2020 to 2021). Chronic progressive interstitial lung disorder characterized by the replacement of the lung tissue by connective tissue, leading to progressive dyspnea, respiratory failure, or right heart failure. "We initially examined repression of the E3 ubiquitin ligases SIAH1, SMURF1, and SMURF2, which have been identified as targets of miR-424 in several cancers as well as pulmonary fibrosis." (PMID 32117091, 2020).
renal carcinoma (2 papers, 2016 to 2022). A carcinoma arising from the epithelium of the renal parenchyma or the renal pelvis. "Co-immunoprecipitation in the renal cancer cell line CAKI which expresses wild type pVHL, showed that both endogenous USP9X and Smurf1 interact with pVHL (lane 2 versus lane 3 and 4)." (PMID 27517496, 2016). "By further considering well-studied oncogenes, we focused on SMAD specific E3 ubiquitin protein ligase 1 (SMURF1) and Enhancer of zeste homolog 2 (EZH2) that extensively regulate gene expression and thereby promote tumorigenesis in various carcinomas, including renal cancer." (PMID 35562342, 2022).
tuberculosis (2 papers, 2022 to 2023). A chronic, recurrent infection caused by the bacterium Mycobacterium tuberculosis. "Smurf1-deficient macrophages were more permissive to M. tuberculosis replication and Smurf1-deficient mice succumb more quickly than wild-type mice to tuberculosis, due to impaired delivery of M. tuberculosis-containing phagosomes to autophagosomes." (PMID 35832792, 2022). "In addition to virophagy and mitophagy, Smurf1 was demonstrated to be required for xenophagic clearance of the intracellular bacteria Mycobacterium tuberculosis, the causative agent of tuberculosis in humans." (PMID 35832792, 2022).
acute lung injury (1 paper, 2025). A condition of lung damage that is characterized by bilateral pulmonary infiltrates (pulmonary edema) rich in neutrophils, and in the absence of clinical heart failure. "We hypothesized that increased kindlin-2 expression via the inhibition of SMURF1 mediates EC inflammatory responses relevant to acute lung injury (ALI)." (PMID 40076507, 2025).
autism (1 paper, 2024). Persistent deficits in social interaction and communication and interaction as well as a markedly restricted repertoire of activity and interest as well as repetitive patterns of behavior. "Moreover, SMURF1 was significantly associated with ASD risk as a de novo splice site variant, as recently described by the Autism Sequencing Consortium patient in the Hartwell Autism Research and Technology Initiative (iHART) cohort." (PMID 38572415, 2024).
B-cell lymphoma (1 paper, 2023). "In addition to its roles in skeletal development, SMURF1 may function as an oncoprotein through regulation of the levels of the tumor suppressor RhoB, leading to promotion of tumor metastasis and initiation, which may provide the reason why B-cell lymphoma developed in the girl." (PMID 36911671, 2023).
brain tumor (1 paper, 2022). "High expression of Smurf1 plays a vital role in brain tumor progression by mediating aberrant cell signaling pathways." (PMID 34614303, 2022). "Moreover, overexpressed Smurf1 plays a pivotal role in brain tumor." (PMID 34614303, 2022).
breast tumor (1 paper, 2018). "Our data showed that SMURF1 depletion by lent-virus based shRNA decelerated breast tumor growth." (PMID 29433542, 2018).
Cerebral ischemia (1 paper, 2025). Restriction of arterial blood supply to the brain associated with insufficient oxygenation to support the metabolic requirements of the tissue. "Studies have indicated the role of SMOX signaling in neuroprotection through various pathways, including antioxidant signaling via Nrf2 in experimental stroke, neuroinflammation in cerebral ischemia via IL6/TNFa, and miR-340-5p/Smurf1 signaling in spinal cord injury." (PMID 40001462, 2025).
diabetic kidney disease (1 paper, 2022). Progressive kidney disorder caused by vascular damage to the glomerular capillaries, in patients with diabetes mellitus. "miR-154-5p regulates the TGFβ1/Smads pathway through Smurf1 ubiquitination and promotes the fibrosis process of diabetic kidney disease." (PMID 35126820, 2022).
Epileptic encephalopathy (1 paper, 2015). A condition in which epileptiform abnormalities are believed to contribute to the progressive disturbance in cerebral function. "(For example, a TANC2 variant in a patient with intellectual disability and febrile seizures and in a patient with ASD, and a SMURF1 variant in a patient with epileptic encephalopathy)." (PMID 25763846, 2015).
esophageal carcinomas (1 paper, 2018). A primary or metastatic malignant neoplasm involving the esophagus. "Several clinical studies also showed that SMURF1 was amplified in the chromatin in pancreatic and esophageal carcinomas." (PMID 29433542, 2018).
folate deficiency (1 paper, 2022). A nutritional condition produced by a deficiency of FOLIC ACID in the diet. "HMeDIP-PCR revealed that binding of these Shh-related genes (Gli2, Hhatl, Smurf1, and Gsnk1g3) to 5hmC was significantly increased upon folate deficiency." (PMID 36199572, 2022).
head and neck cancer (1 paper, 2014). A primary or metastatic malignant neoplasm affecting the head and neck. "Our findings suggest that SMURF1 inhibition of BMP signaling in CSC-like populations potentiates the long-term survival and maintenance of CSCs in head and neck cancer." (PMID 25471937, 2014). "In this study, we investigated whether the E3 ligase SMURF1 is involved in regulating BMP signaling and the maintenance of CD44high cells in head and neck cancer cell lines." (PMID 25471937, 2014).
Hepatic steatosis (1 paper, 2018). Steatosis is a term used to denote lipid accumulation within hepatocytes. "Here, we show that mice deficient for ubiquitin ligase (E3) Smad ubiquitin regulatory factor 1 (Smurf1) spontaneously develop hepatic steatosis as they age and exhibit the exacerbated phenotype under a high-fat diet (HFD)." (PMID 30566427, 2018). "Here, we report that Smurf1 induces non-proteolytic ubiquitination of PPARγ and inhibits PPARγ transcriptional activity in hepatocytes, thereby acting as a critical safeguard against the development of hepatic steatosis." (PMID 30566427, 2018).
lymph node metastasis (1 paper, 2019). "The higher expression of Smurf1 was also found to be associated with larger tumor size, poorer histological type, and lymph node metastasis." (PMID 30631050, 2019).
nephrotoxicity (1 paper, 2017). Toxicity that causes injury to the kidney or damages its function. "Also, BMPR1A, SMAD7, SMURF1 have been reported to be related to kidney fibrosis which is one key indicator of kidney nephrotoxicity." (PMID 28414804, 2017).
non-small cell lung carcinoma (1 paper, 2021). A group of at least three distinct histological types of lung cancer, including non-small cell squamous cell carcinoma, adenocarcinoma, and large cell carcinoma. "In the study, it was observed that the Smurf1 positive non-small cell lung cancer patients have better chances at survival; therefore, the negative regulation of Smurf1 results in lung carcinogenic due to interruption in TGF-β signaling." (PMID 34769401, 2021).
Osteopenia (1 paper, 2014). Osteopenia is a term to define bone density that is not normal but also not as low as osteoporosis. "Our work indicates targeting Smurf1 for inhibition could be an accessible strategy to discover BMP-sensitizers that might be applied in future clinical treatments of bone disorders such as osteopenia." (PMID 24828823, 2014).
periodontitis (1 paper, 2022). An acute or chronic inflammatory process that affects the tissues that surround and support the teeth. "Decreased miR-17 levels and increased Smurf1 expression were observed in PDLCs from periodontitis-affected periodontal ligament tissue, and both had an impact on the differentiation potential of PDLCs." (PMID 36077334, 2022).
renal failure (1 paper, 2014). "Consistently, our analysis detected the up regulation of SMURF1, suggesting it may contribute to the progression of renal failure through its ubiquitination of SMAD7." (PMID 24997640, 2014). "For the rest four hub genes, SRSF1, CAND1, SMURF1, and YWHAE, no previous report of their association with renal failure has been proposed before." (PMID 24997640, 2014).
Right ventricular hypertrophy (1 paper, 2020). In this case the right ventricle is more muscular than normal, causing a characteristic boot-shaped (coeur-en-sabot) appearance as seen on anterior- posterior chest x-rays. "As a BMPR2 signaling suppressor, Smurf1 knockout mice show right ventricular hypertrophy and decreased pulmonary microvascular remodeling." (PMID 33110392, 2020).
scleroderma (1 paper, 2019). Scleroderma is a rare autoimmune connective tissue disorder characterized by abnormal hardening of the skin and, sometimes, other organs. "Interestingly, overexpression of SMURF1/2 did not change TGFR1 levels under basal and TGF-β-stimulated conditions in scleroderma fibroblasts, while it reduced both basal and TGF-β stimulated levels of TGFR1 in normal skin fibroblasts." (PMID 30696809, 2019).
silicosis (1 paper, 2024). Silicosis is a respiratory disease caused by breathing in (inhaling) silica dust. "Researchers also found that miR-125a-5p, derived from exosomes of macrophages from silicosis patients, inhibits Smurf1 expression, thereby mediating the differentiation of lung fibroblasts to myofibroblasts, which plays a key role in silicosis." (PMID 39113708, 2024).
spinal cord injury (1 paper, 2021). Penetrating and non-penetrating injuries to the spinal cord resulting from traumatic external forces (e.g., WOUNDS, GUNSHOT; WHIPLASH INJURIES; etc.). "In LPS-induced SCI (Spinal cord injury) microglia cells and lncRNA Xist, which interacts with miR-27a to mediate the downstream target gene of Smurf1 expression, alleviated the apoptosis and inflammatory injury of microglia cells after SCI through activating miR-27a/Smurf1 axis." (PMID 34178980, 2021).
steatosis (1 paper, 2018). Increased lipid within the cytoplasm of cells. "In young BL mice (10–12 weeks of age) that had yet to develop steatosis, loss of Smurf1 increased the expression of total Pparγ (about 1.57-fold) when the mice were fed on ND, suggesting that Smurf1 has a direct causal effect on Pparγ expression." (PMID 30566427, 2018). "To directly test if the increased PPARγ activity and expression are responsible for steatosis associated with Smurf1 loss, we treated a group of WT and Smurf1KO mice from the BL background with the PPARγ antagonist GW9662." (PMID 30566427, 2018). "Thus, the steatosis associated with Smurf1 loss is likely the result of an overall gain in body fat content in both strain backgrounds, suggesting that Smurf1 may have a systemic role in regulating lipid metabolism." (PMID 30566427, 2018). "Given our current finding of Smurf1 in protecting the liver from steatosis, a viable strategy to treat NAFLD may be to curtail the transcriptional activity of PPARγ by turning on Smurf1-mediated non-proteolytic ubiquitin modification." (PMID 30566427, 2018).
tongue cancer (1 paper, 2019). A malignant neoplasm affecting the tongue. "Differential expression profiling of the tongue cancer cohort triaged based on the stage, pathology identified multiple candidate markers; JAM2, SMURF1, LY6E, MFN1 and SUPT16H." (PMID 31310629, 2019).
Ureteral obstruction (1 paper, 2014). Obstruction of the flow of urine through the ureter. "It is reported that reduction of Smad7 due to the overexpression of Smurf1 in unilateral ureteral obstruction kidneys plays an important role in the progression of tubulointerstitial fibrosis, which a harmful process leading inevitably to renal function deterioration." (PMID 24997640, 2014).